HTRA1 (HtrA serine peptidase 1)
Diseases named in the same sentence as HTRA1 in open-access papers (continued):
Sharing a sentence is not in itself a finding about the gene and the disease.
COVID-19 (2 papers, 2022 to 2025). A disease caused by infection with severe acute respiratory syndrome coronavirus 2. "The GWAS catalog database shows that several genomic variants in HTRA1 have been previously associated with COVID-19." (PMID 40149929, 2025). "We identified four variants associated with COVID-19 severity with genome-wide significance (rs58027632 in KIF19; rs736962 in HTRA1; rs77927946 in DMBT1; and rs115020813 in LINC01283)." (PMID 40149929, 2025).
craniosynostosis (2 papers, 2013 to 2016). Craniosynostosis is defined as the premature fusion of one or more cranial sutures leading to secondary distortion of skull shape resulting in skull deformities with a variable presentation. "While previous research has indicated crosstalk between the Htra1/Igf1, Akt, and Wnt pathways after thyroid exposure leading to a synergistic effect, further characterization of the signaling cascade is required to determine how thyroid exposure results in craniosynostosis." (PMID 27959899, 2016).
cystitis (2 papers, 2015 to 2023). Inflammation of the urinary bladder. "First, validation of NNMT, GALK1, and HTRA1 and other candidates tightly correlated with BCa stage needs to be performed using larger patient cohorts of BCa including benign conditions such as cystitis, samples with hematuria, as well as other tumors from the urogenital tract (prostate, and renal)." (PMID 37834386, 2023). "Dysregulation concerning BCa has been reported only in one study, where tissue levels of HTRA1 were undetectable in a few urothelial cancer cell lines but significantly higher amounts were found in urine from cancer patients compared with both healthy subjects and patients with cystitis." (PMID 37834386, 2023).
depression (2 papers, 2013 to 2023). "When considering NPDs of interest, depression, and anxiety alone, the strongest pleiotropic effects of single genes, i.e. highest number of associations with disorders, were observed for PFN2, HTRA1, SCRN1, ATAT1, and SYN3." (PMID 37461513, 2023). "Accordingly, reduced Htra1 and Htr2c expressions in XY mice are consistent with the increased depressive-like behaviors observed in that group and together suggests a sexual dimorphism aspect to the low serotonin hypothesis of depression." (PMID 24199867, 2013).
Gestational Diabetes Mellitus (2 papers, 2022 to 2023). "Moreover, plasma HTRA1 maternal levels were found significantly increased in patients with PE, spontaneous preterm birth (sPTB), and gestational diabetes mellitus (GDM)." (PMID 37232715, 2023). "In particular, we evaluated a possible role of HtrA1 as an early marker of gestational diabetes mellitus (GDM) in the first trimester of gestation." (PMID 36359548, 2022).
gingivitis (2 papers, 2014 to 2016). A disorder involving inflammation of the gums; may affect surrounding and supporting structures of the teeth. "In gingivitis sections, HtrA1 positivity resulted uniformly distributed in all layers." (PMID 24979214, 2014). "Fibroblasts and collagen fibers resulted negative for HtrA1 in all cases, except in gingivitis where fibroblasts were faintly positive." (PMID 24979214, 2014). "Results of quantitative real-time PCR indicate that HtrA1 transcript was present in first trimester placental tissue (positive control) (data not shown) and in gingivitis at levels that are ∼2 fold higher than in healthy gingiva." (PMID 24979214, 2014).
glaucoma (2 papers, 2024 to 2025). Increased pressure in the eyeball due to obstruction of the outflow of aqueous humor. "Surprisingly, increased expression of p62, a marker for autophagic flux, was prominent in the GC layer of 21m Htra1–/– mice, and this phenomenon has been observed in age-related retinal degeneration and glaucoma models." (PMID 39927462, 2025).
glioma (2 papers, 2021 to 2024). A benign or malignant brain and spinal cord tumor that arises from glial cells (astrocytes, oligodendrocytes, ependymal cells). "High HTRA1 expression was associated with the more aggressive glioma molecular subtypes, mesenchymal and classical subtypes." (PMID 38334007, 2024). "However, the molecular mechanisms underlying HTRA1 activity in glioma requires further investigation." (PMID 38334007, 2024). "Besides, high HTRA1 expression was found to be associated with low M1 macrophage infiltration, low immune reactivity and high tumor purity in TCGA glioma samples." (PMID 38334007, 2024). "In this study, we analyzed publicly available databases to explore the expression pattern of HTRA1 in glioma tissues and the correlation between HTRA1 expression levels and the prognosis of glioma patients." (PMID 38334007, 2024). "Our work explores the role of HTRA1 in glioma cells and also provides new insights for the infiltration of glioma cells." (PMID 38334007, 2024). "High HTRA1 expression was also significantly correlated with worse prognosis in glioma patients in the TCGA cohort." (PMID 38334007, 2024). "In vivo experiments with isogenic HTRA1 knockdown cells indicated that HTRA1 facilitated the infiltration of glioma and shortened the survival period of nude mice." (PMID 38334007, 2024). "The HTRA1 serine protease has been found to have the ability to promote glioma cell proliferation, migration/invasion, and to inhibit tumor apoptosis, in vitro and in vivo." (PMID 38334007, 2024). "Overall, we demonstrated that HTRA1 expression levels were significantly increased in higher grade gliomas and that high expression was correlated with worse prognosis in glioma patients." (PMID 38334007, 2024). "In addition, in situ xenograft tumor model was employed to explore the role of HTRA1 in glioma growth in vivo." (PMID 38334007, 2024). "Our work indicates that HTRA1 might promote the development of human glioma by enhancing cell migration and invasion." (PMID 38334007, 2024). "In summary, our findings suggested that HTRA1 functioned as an oncogene in glioma and might be a potential prognostic marker and therapeutic target for gliomas." (PMID 38334007, 2024). "Then we found the expression level of HTRA1 was the highest among 52 serine proteases and expression level of HTRA1 in gliomas was significantly higher than in normal tissues, and high HTRA1 expression predicted poor prognosis of glioma patients." (PMID 38334007, 2024). "Thus, it is likely that small molecules that inhibit HTRA1 may be beneficial for glioma treatment in vivo and further studies are required for confirmation." (PMID 38334007, 2024). "Our current research provides evidences that HTRA1 might be a carcinogenic gene in glioma cells." (PMID 38334007, 2024). "Our results indicate that HTRA1 promotes the proliferation and migration of GBM cells in vitro and in vivo, and thus may be a potential target for treatment in gliomas." (PMID 38334007, 2024). "In this study, we found increased HTRA1 expression in gliomas relative to nontumor brain tissue." (PMID 38334007, 2024). "However, to the best of our knowledge, no other studies to date have illuminated the function of HTRA1 in human glioma." (PMID 38334007, 2024).
heart failure (2 papers, 2024 to 2025). Inability of the heart to pump blood at an adequate rate to meet tissue metabolic requirements. "Validation using external datasets and analyses revealed that HTRA1 is highly expressed in myocardial tissues of heart failure patients, while RT-qPCR results indicated low expression of HTRA1 in the plasma of HF patients." (PMID 40406620, 2025). "The results showed that, compared to normal samples, HMGN2, HTRA1, LTBP2, and MFAP4 were significantly upregulated in heart failure, while MYH6 was downregulated (p < 0.001)." (PMID 40406620, 2025).
intracerebral hemorrhage (2 papers, 2022 to 2023). A cerebrovascular disorder characterized by bleeding into one or both cerebral hemispheres including the basal ganglia and the cerebral cortex. "Across subtypes, the highest hit rate (HR) was intracerebral hemorrhage (ICH, 7/18 = 38.9%), particularly with the etiological subtype of structural vasculopathy (4/4 = 100%, PVs in ENG, KRIT1, PKD1, RNF213); followed by ischemic small vessel disease (SVD, 15/48 = 31.3%; PVs in NOTCH3, HTRA1, HBB)." (PMID 36580209, 2023).
invasive breast carcinoma (2 papers, 2012 to 2022). A carcinoma that infiltrates the breast parenchyma. "Down regulation of DST and HTRA1 has been associated with progression to invasive breast cancer and was found in our data-set." (PMID 23236365, 2012). "On the other hand, HTRA1 was found to be significantly expressed within the breast normal ductal glands and its expression is significantly downregulated in invasive breast cancer in general." (PMID 36536459, 2022).
leukodystrophy (2 papers, 2018 to 2021). Leukodystrophies are a group of rare, progressive, metabolic, genetic diseases that affect the brain, spinal cord and often the peripheral nerves. "While it had been shown that heterozygous HTRA1 variants make up the second largest proportion of VCI-SVD patients in Taiwanese Han-Chinese, Japanese, Italian and French cohorts, similar findings have so far not been reported in other leukodystrophy genetic sequencing studies." (PMID 33597917, 2021).
liver cancer (2 papers, 2012 to 2018). An epithelial or non-epithelial malignant neoplasm that arises from the liver. "The downregulation of HtrA1 has also been associated with poor prognosis in stomach, breast and liver cancers." (PMID 30131069, 2018). "Contrary to our results, the downregulation of HtrA1 in stomach, breast, and liver cancers has been associated with poor outcomes." (PMID 30131069, 2018).
meningioma (2 papers, 2020 to 2023). A generally slow growing tumor attached to the dura mater. "AKT1 meningiomas displayed high relative levels of HTRA1 and transferrin genes relative to KLF4 tumors, while KLF4 tumors overexpressed CEACAM6, DEGS2, and TSPAN12 relative to AKT1 tumors." (PMID 36937440, 2023). "Conversely, our analyses revealed an opposing trend of increasing protein expression in high-grade meningioma, yet we also observed downregulation of HTRA1 transcript LFC." (PMID 33167358, 2020). "Following RT-qPCR, we identified a significant reduction in relative expression for CST3, LAMP2, PACS1 and HTRA1 in grade III meningioma compared with grade I compatible with our hypothesis that increased abundance of these proteins in the tumour originates from the blood circulation." (PMID 33167358, 2020). "Therefore, in line with our hypothesis, HTRA1 may also derive from the tumour microenvironment of fast-growing grade III meningioma to promote angiogenesis." (PMID 33167358, 2020). "Thus, subject to further investigation, discordantly expressed transcripts/proteins such as HTRA1 and LAMP2 could hold promise as diagnostic blood biomarkers for high-grade meningioma." (PMID 33167358, 2020). "The corresponding transcript levels were validated for PACS1, LAMP2, HTRA1 and CST3 in meningioma tissue." (PMID 33167358, 2020). "Unlike HTRA1, LAMP2 has remained unreported in meningioma until now." (PMID 33167358, 2020). "Notably, we derived a plasma signature of 21 discordantly expressed genes showing positive changes in protein but negative in transcript levels of high-grade meningiomas, including the validated genes CST3, LAMP2, PACS1 and HTRA1, suggesting the acquisition of these proteins by tumour from plasma." (PMID 33167358, 2020).
metastatic disease (2 papers, 2015 to 2020). "Somewhat surprisingly, the overall HtrA1 protein level was significantly lower in CRC tissue as compared to the control, specifically in primary tumors of metastatic disease." (PMID 32486357, 2020).
pancreatitis (2 papers, 2017 to 2024). Inflammation of the pancreas. "Our previous research is expected to identify another HTRA1-mediated mechanism for pancreatitis-initiated PDAC initiation, in which, HTRA1 is significantly up-regulated during pancreatitis." (PMID 38287020, 2024). "Carfilzomib is an innovative candidate drug that can inhibit pancreatitis-initiated PDAC through targeted inhibition of HTRA1." (PMID 38287020, 2024). "Mechanistically, HTRA1 interacted with CDK1 protein, and CDK1 inhibitor reversed the malignant phenotype of PANC-1 and pancreatitis-initiated PDAC activated by HTRA1 overexpression." (PMID 38287020, 2024). "In order to find candidate drugs targeting HTRA1 for the treatment of pancreatitis-initiated PDAC, we first determine the binding pocket of HTRA1 by analyzing its 3D structure." (PMID 38287020, 2024). "In order to test the role of miR-30a-5p in the regulation of inflammation and HTRA1/TGF-β1 signaling pathway by emodin in rat pancreatitis, in vivo miR-30a-5p antagomir experiment was performed." (PMID 29163548, 2017). "Collectively, these results demonstrate that miR-30a-5p/HTRA1 are the target of emodin-mediated attenuation of pancreatic acinar cell injury in pancreatitis, thus providing the foundation for further development of this natural product for medical therapy." (PMID 29163548, 2017). "Pancreatitis is a crucial risk factor for pancreatic ductal adenocarcinoma (PDAC), and our previous study had proved high-temperature requirement protein A1 (HTRA1) exacerbates pancreatitis insult; however, the function and mechanism of HTRA1 in pancreatitis-initiated PDAC is still unclear." (PMID 38287020, 2024). "Our previous research confirmed the high expression of HTRA1 in pancreatitis, which may open up new ideas for the effects and mechanisms of HTRA1 in pancreatitis-induced PDAC." (PMID 38287020, 2024). "Therefore, the upregulation of Htra1 in KC mice can accelerate pancreatitis-initiated PDAC." (PMID 38287020, 2024). "Therefore, HTRA1 may become a critical target for inhibiting the progression of pancreatitis-induced PDAC." (PMID 38287020, 2024). "In this study, we found that miR-30a-5p/HTRA1 may be a potent candidate target of the emodin-mediated attenuation of pancreatic acinar cells injury in pancreatitis, providing the foundation for the development of novel natural products for future medical interventions." (PMID 29163548, 2017). "Therefore, miR-30a-5p silencing induced by its antagomir abrogated the anti-inflammatory activity of emodin in pancreatitis rats, which showed that miR-30a-5p exerted critical regulation in anti-inflammatory effect of emodin by regulating HTRA1/TGFβ1 signaling pathway." (PMID 29163548, 2017). "HTRA1 is high expressed in PDAC, and severs as a critical activator for tumor cells malignant phenotype and pancreatitis-initiated PDAC progression by targeting CDK1-mediated cell cycle." (PMID 38287020, 2024). "Here, we highlighted the potential for inhibiting HTRA1 as a mean to impede pancreatitis-initiated PDAC, and further provided a newly discovered a small molecule drug that can inhibit HTRA1, carfilzomib, as candidate drug for PDAC therapy." (PMID 38287020, 2024). "Due to the importance of HTRA1 in pancreatitis-initiated PDAC, we employed DrugBank’s virtual screening to identify small molecule drug that can inhibit HTRA1 among the approved drug molecules." (PMID 38287020, 2024). "HTRA1 protein expression and the number of MPO-positive cells both significantly increased in the pancreatic tissue of rat pancreatitis compared with those in the control group, and this effect was decreased by emodin at a dose of 60 mg·kg−1." (PMID 29163548, 2017). "Therefore, miR-30a-5p acts as a novel drug target of emodin to prevent spontaneous activation of the HTRA1/TGF-β1 signaling pathway, which has potential implications in pancreatitis pathologies." (PMID 29163548, 2017).
adenoma (1 paper, 2016). A neoplasm arising from the epithelium. "In this regard, it is significant that repression of Htra1 is mediated by MBD2, the deficiency of which we have previously shown to strongly suppress the majority of adenomas in the ApcMin+ mouse." (PMID 27388476, 2016). "An implication of these studies is that Htra1 status will influence adenoma formation in ApcMin+ mice, a hypothesis we are currently testing." (PMID 27388476, 2016). "The fact that adenomas do eventually form in this model suggests that MBD2-mediated suppression of target genes such as Htra1 may be relevant to a subset of lesions." (PMID 27388476, 2016).
allergic rhinitis (1 paper, 2020). Inflammation of the nasal mucous membranes caused by an IgE-mediated response to external allergens. "The aim of the present study was to analyze serum levels of tumor suppressors—HTRA1, HTRA2, HTRA3 proteins and Il-12—in pediatric patients and control group so as to consider its role in assessing the antioncogenic potential in atopic asthma (AA) and allergic rhinitis (AR)." (PMID 32560402, 2020).
Allergy (1 paper, 2020). An allergy is an immune response or reaction to substances that are usually not harmful. "Higher levels of HTRA1–3 proteins than controls in allergy and not in mastocytosis may suggest that synthesis of these proteins is more intensive in allergic disorders." (PMID 32560402, 2020).
angina pectoris (1 paper, 2024). The symptom of paroxysmal pain consequent to MYOCARDIAL ISCHEMIA usually of distinctive character, location and radiation. "The genetically predicted increase in plasma HTRA1 levels was associated with reduced risk of angina pectoris, consistent with the PWMR results." (PMID 38989470, 2024).
asthma (1 paper, 2020). "We suggest that the higher level of HTRA3 and HTRA1 in children with atopy and asthma might be connected with their known interactions with TGFβ." (PMID 32560402, 2020).
Autoimmunity (1 paper, 2025). The occurrence of an immune reaction against the organism's own cells or tissues. "The podocyte-focused expression of PLA2R1, NTNG1, HTRA1, and NDNF is intriguing, highlighting antigen-initiated autoimmunity as causing podocyte injury and the subsequent MN pathogenesis." (PMID 40149392, 2025).
CADASIL syndrome (1 paper, 2023). "For example, CADASIL syndrome could be caused by NOTCH3 or HTRA1 mutations, both account for a significant number of SVD and/or ICH patients in our population." (PMID 36580209, 2023).
cholesteatoma (1 paper, 2014). A pathologic process characterized by the proliferation of keratinizing squamous epithelium resulting in the accumulation of keratin and cells in the middle ear and/or mastoid. "HTRA1 may therefore also have a role in the erosion of the ossicles that that is associated with cholesteatoma disease." (PMID 25093596, 2014). "Among the up-regulated proteases in cholesteatoma tissues, HTRA1 (High temperature requirement A1, serine protease) is a novel finding which has interesting characteristics." (PMID 25093596, 2014).
colon adenocarcinoma (1 paper, 2016). "On the cellular level, HTRA1 depletion causes multiple phenotypes including acceleration of cell growth, centrosome amplification and polyploidy in SW480 colon adenocarcinoma cells as well as in primary mouse embryonic fibroblasts (MEFs)." (PMID 27388476, 2016).
colon adenoma (1 paper, 2016). An adenoma that arises from the colon. "To obtain in vivo evidence, we analysed Htra1 expression in the intestines of ApcMin+ mice, a well established model of early events in intestinal tumorigenesis, and in polyps of colon adenomas arising in these animals." (PMID 27388476, 2016).